TGFBR1 (transforming growth factor beta receptor 1)
Diseases named in the same sentence as TGFBR1 in open-access papers (continued):
Sharing a sentence is not in itself a finding about the gene and the disease.
tumor (continued). "When data for both types of tumour were pooled, a significant increase in cancer risk was associated with TGFBR1*6A carriers (OR: 1.60; 95% CI: 1.10–2.31)." (PMID 19538729, 2009). "Different TGFBR1 allelic variants have been associated with susceptibility to develop different types of tumours." (PMID 19930569, 2009). "Our results show that the GCG repeat at exon 1 of the TGFBR1 gene is a specific target for MSI tumours (p = 0.039), but the frequency of mutations is low (2/14, 14.29%)." (PMID 19538729, 2009). "Two meta-analyses, which included 12 case-control studies, have shown that TGFBR1*6A is a candidate tumour-susceptibility allele, is present in 13.7% of the general population and increases the risk of cancer by approximately 24%." (PMID 19538729, 2009). "We subsequently genotyped Tgfbr1 gene from the tumor cells to determine if this deletion event was caused by a somatic mutation." (PMID 17705854, 2007). "Two common alleles in the TGFBR1 gene, TGFBR1*6A and Int7G24A, A allele, which reside in exon 1 and intron 7, respectively, have been reported to act as low-penetrance tumour susceptibility alleles." (PMID 17848956, 2007). "Several studies including a meta-analysis of 12 studies have demonstrated that TGFBR1*6A acts as a low-penetrance tumour susceptibility allele in the development of colon, cervix, breast, and ovarian cancer as well as haematological malignancies." (PMID 17848956, 2007). "Approximately 14% of the general population carries at least one copy of TGFBR1*6A, which makes it the most common candidate tumor susceptibility allele reported to date." (PMID 15385056, 2004). "Indeed, we and others have previously shown that epithelial-specific loss of Tgfbr1/2 or Smad4 accelerates tumourigenesis in the context of Apc and Kras mutations, consistent with key tumour-suppressive roles for epithelial TGFβ signalling in CRC." (PMID 36477656, 2022). "It remains unclear if the differences in TGFBR1*6A risk association correlate with geographical location, ethnicity, age, tumor stage, and other confounding factors such as other polymorphism frequencies, lifestyle, and environment." (PMID 35853889, 2022). "Interestingly, we previously demonstrated that loss of Tgfbr1/Alk5 promotes the dedifferentiation and tumour-initiating capability of Apc/Kras-mutant differentiated intestinal epithelial cells." (PMID 36477656, 2022). "Subsequently, the target-disease association related to TGFBR1 in neoplasm and skeletal system disease could be determined and viewed by using the Open Targets Platform." (PMID 32582282, 2020). "TGFBR1*6A, a polymorphic allele of TGFBR1, was detected in the TGFBR1 tumor-specific mutations." (PMID 31827763, 2019). "To determine whether these somatic mutations are specific for MSI tumours, we analysed tumour DNA from 55 cases that were homozygous for the TGFBR1*9A allele and were MSI-negative." (PMID 19538729, 2009). "Therefore, the pre-existinganti-cancer activity of high-risk score patients may be limited by high levels of tumor-infiltrating macrophages (M2) and overexpression of many inhibitory immune checkpoints such as TGFBR1 and KDR." (PMID 36090900, 2022). "The additional findings of an overrepresentation of TGFBR1*6A heterozygotes and homozygotes among patients with a diagnosis of cancer as compared with the general population led us to postulate that TGFBR1*6A might act as a tumor susceptibility allele." (PMID 15385056, 2004). "These pathway-level changes were accompanied by reduced expression of transcripts frequently associated with tumor-promoting programs, such as SERPINA1, MDM2, PDGFA, TGFBR1/2, and SPINK1." (PMID 41596590, 2026). "Our findings demonstrate that NPC1 promotes HCC progression by stabilizing TGFBR1 and facilitating tumor cell migration." (PMID 39762312, 2025). "GEPIA2 analysis showed a significant upregulation of TGFBR1 in tumor biopsies compared to normal tissues (p < 0.01)." (PMID 41373412, 2025).
tumor (continued). "Targeting transforming growth factor beta receptor 1 (TGFβR1) in combination with gemcitabine increases drug perfusion into the tumor core and improves the therapeutic efficacy in pancreatic cancer." (PMID 40248695, 2025). "Using the Tgfbr1/Pten double KO mouse model, the application of an αTim- 3 antibody reduced Treg count and restored IFNγ production haltering tumor growth." (PMID 40666515, 2025). "The colocalization of CCN2/TGF-β/TGFBR1 in the membrane of S100A6+ tumor cells further confirmed the interaction pair." (PMID 39095854, 2024). "mIF images visualized the spatial proximity of S100A6+ TGFBR1+ tumor cells and FAP+ CCN2+ fibroblasts." (PMID 39095854, 2024). "Previous research has confirmed the interaction between tumor-enriched angiogenic ECs and Tumor-associated Macrophages (TAMs) through TGFB1 (angiogenic ECs) ⇔ TGFBR1 (Mye1, TAMs)." (PMID 39026350, 2024). "The impact of tumour-cell-derived circRNAs on the surrounding vascular function has been touched upon, as illustrated by the circEHBP1/miR-130a-3p/TGFbR1 axis." (PMID 38203852, 2024). "In the HBx dysregulated HBV-HCC pathways, this panel of MIRNAs can influence a number of genes in the TGF-B/SMAD pathway by targeting validated gene targets like TGFBR1/SMAD3/, CDKN1A and MYC to influence both oncogenesis and the loss of tumor suppression." (PMID 38256049, 2024). "Pretreatments of mice with patient-derived xenograft tumours with TGFBR1 inhibitor galunisertib/LY2157299 led to reduced tumour growth and ascites development, suggesting potential as a maintenance therapy to limit recurrence." (PMID 38622286, 2024). "The Tumor Immune Estimation Resource (TIMER) database was further employed to explore the relationship between TGFBR1 and PDCD1 gene expression in various human tumors." (PMID 38441961, 2024). "In contrast, overexpression of TGFBR1-WT in the MHCC97H-SH-GPR56 group promoted tumor growth and metastasis, while overexpression of TGFBR1-S165D showed no significant pro-cancer effects." (PMID 39353900, 2024). "For instance, experimental evidence demonstrates that haploid loss of TGFBR1 and TGFBR2 impairs SMAD signaling and promote tumor progression in mouse models." (PMID 38753874, 2024). "Next, the effects of ISO and TGFBR1 knockdown on tumor cell migration and invasion were determined by transwell assay and scratch assay." (PMID 39364054, 2024). "To further demonstrate that TGFBR1 overactivation promotes Sertoli cell transdifferentiation into granulosa-like tumor cells, we took advantage of the membrane-targeted tdTomato (mT)/membrane-targeted EGFP (mG) mouse, a dual fluorescence reporter." (PMID 38067144, 2023). "TGFBR1 was found to be significantly upregulated in tumor tissue compared to non-tumor tissue in 18 of 20 patients." (PMID 36901700, 2023). "Myofibroblast CAFs (myCAFs) and endothelial TGFBR1 were identified as a potential targets for TGFB2 from basal-like tumor cells." (PMID 37633924, 2023). "Collectively, we herein provide genetic evidence supporting the transdifferentiation of Sertoli cells into granulosa-like tumor cells during tumorigenesis induced by TGFBR1 overactivation in these cells." (PMID 38067144, 2023). "Our discoveries identified WFDC3 as a tumor suppressor that facilitates estrogen-induced inhibition of metastasis through the ERβ/TGFBR1 signaling axis." (PMID 37443102, 2023). "The expression of TGFBR1 in HCC tissues was generally upregulated compared with that in adjacent non-tumor tissues." (PMID 36901700, 2023).
tumor (continued). "Among these genes, SPINT2, LNX1, FOXA2, and SOSTDC1 were reported to be related to tumor progression, whereas TYROBP, TREM2, IL23R, CSF2RB, TRAF1, and TGFBR1 were closely associated with immune response." (PMID 36611170, 2023). "For example, CA-enriched blood-vessel-specific TGFBR1 kinase, which is an important regulator of cardiovascular health and tumor vasculature." (PMID 37175790, 2023). "A recent tumor study found that TGFBR1 modified T-cell function by blocking the PD-1/PD-L1 checkpoint, to achieve an anti-tumor effect." (PMID 35865012, 2022). "As the irreplaceable receptor of TGF-β1, TGFBR1, which is observed in different tumor types, participates in tumor immunological reactions." (PMID 35837087, 2022). "Activated TGFBR1 phosphorylates the SMADs protein family, which leads to signal transduction into cells, thus regulating the expression of target genes and affecting tumor progression." (PMID 36248424, 2022). "Consistent with the mRNA expression of Wisp1, WISP1 protein was strongly localized to TGFBR1-CA ovaries, particularly in the tumor foci, in contrast to the limited immunoreactive signals in control ovaries." (PMID 35565312, 2022). "We found Somatic mutations in TGFBR1, TGFBR2, and TGFBR3 genes in primary tumor and metastases samples of long-responder patients." (PMID 34833459, 2021). "For instance, TGFβ has been shown to be potently tumour suppressive in disease initiation as illustrated by the frequent mutations to signalling components, TGFβ-receptor-2 (TGFBR2), TGFBR1 and SMAD4 in human PDAC." (PMID 34638468, 2021). "Conversely, release of miR-142-3p in the small EVs was found to reduce TGFBR1 activity and promote tumour growth both in vitro and in vivo." (PMID 32054041, 2020). "Further evaluation of miR-142-3p, for its role in promoting cancer growth, found it to target TGFBR1, reducing its expression in donor cells leading to suppressed tumour growth and colony formation." (PMID 32054041, 2020). "Particularly, the candidate gene TGFBR1 is reported to be involved in multiple biological functions in tumor." (PMID 32582282, 2020). "One study demonstrated that VEGF and TGFBR1 (ALK5) inhibitors can synergistically promote tumor angiogenesis by potentially blocking the downstream effectors of ALK5 such as Smad2 and Smad3." (PMID 32993787, 2020). "On the other hand, TGFBR1 inhibitor SB431542 is able to decrease tumour burden by eliminating the immune suppression induced by Tregs and regulatory B cells (Bregs) and restoring normal T cell function." (PMID 33114183, 2020). "Several preclinical studies have recently underscored the relevance of TGFBR-1 targeting in order to activate an anti-tumor immune response." (PMID 33553157, 2020). "Overall, these results indicate that blocking TGFβ signaling through TGFBR1 inhibition is sufficient to trigger the expansion of tumor-initiating progenitors in vitro." (PMID 31257133, 2019). "For examples, TGFBR1 is identified as a direct target gene of miR-769-5p, and miR-769-5p exerts the tumor-repressive effects on NSCLC." (PMID 30601026, 2019). "Empty-vector control (EGFP) and kinase-inactive (dominant-negative, dn) TGFBR1-expressing MDA-MB-231 cells were inoculated into immune-deficient mice, alone or as admixture with non-tumor diploid 208F fibroblasts." (PMID 29921235, 2018). "Transforming growth factor beta 1 (TGFB1), secreted in the tumor micro-environment, modulates cancer growth through the specific binding to TGFBR1 and subsequent activation of intracellular signals." (PMID 30115852, 2018). "Our previous work showed that the TGFBR1 activity dramatically affects the tumor cell-intrinsic metastatic potential." (PMID 29921235, 2018). "We then explored the role of miR-655 in PC cells, which demonstrated the tumor suppressive role of miR-665 via targeting TGFBR1 and TGFBR2 by regulating SMAD2/SMAD3 pathway." (PMID 29899418, 2018).
tumor (continued). "Immunohistochemical staining showed increased TGFBR1 staining intensities in xengraft tumors of the miR-769-5p antagomir group than in the NC group, indicating that tumor cell proliferation was increased when miR-769-5p was reduced." (PMID 29371929, 2017). "A combined deletion of important tumour suppressors Pten and Tgfbr1 (2cKO) leads to a fast and full penetration of HNSCC tumorigenesis in these mice." (PMID 28401653, 2017). "Conditional knockout of Tgfbr1 in epithelia induces an enhanced paracrine effect of TGF-β1 on tumor stroma." (PMID 28592285, 2017). "To evaluate the effect of anti‐TIM3 therapy on the spontaneous tumor growth, we employed the chemopreventive experiment by utilizing the Tgfbr1/Pten 2cKO mice." (PMID 28102051, 2017). "The functional requirement for upregulated MAPK pathway following Tgfbr1 loss was highlighted by MEK inhibition, which markedly reduced the number of tumours arising with top-down morphology." (PMID 28622298, 2017). "Taken together, these data demonstrate that constitutively active TGFBR1 promotes cell proliferation, inhibits cell differentiation, and alters tumor microenvironment by enhancing angiogenesis." (PMID 27344183, 2016). "Copy number analysis also revealed that loss of heterozygosity occurred in both TGFBR1 and TGFBR2 genes including in tumours with missense mutations in TGFBR2." (PMID 27558455, 2016). "TGFBR2 is known to act as a tumor suppressor by initiating the TGF-β signaling pathway through recruitment of TGFBR1, thus activating downstream signaling to negatively regulate cell proliferation." (PMID 27120811, 2016). "We also define a functional role by which the CEA B3 domain interacts with TGFBR1, potentially inactivating the tumor suppressor function of TGF-β signaling." (PMID 27100181, 2016). "Tumor formation in the TGFBR1-CAAcre ovary was accompanied by a disruption of follicular development, with loss of follicle boundary and presence of multiple oocytes containing follicles (red arrows), compared with age-matched controls." (PMID 27344183, 2016). "As expected, KRT8 and KRT17/19 were localized to ovarian surface epithelia of control and TGFBR1-CAAcre mice, with low to undetectable expression in the tumor tissues at the age of 2 months." (PMID 27344183, 2016). "Treatment of miR122 positive cells with an inhibitor of TGFBR1 activation, abolished tumor dormancy program and recovered cell proliferation rate through a Smad-independent TGF-β response." (PMID 27612430, 2016). "The expression levels of anti-Let-7 target genes (in humans: HMGA2, IGF2BP2, and LIN28B; in mice: Igf2bp2, Nras, and Tgfbr1) were examined in each tumor mass and brain tissue from mice." (PMID 27102443, 2016). "In patients diagnosed with small tumours, those with higher TGFBR1 mRNA levels in the tumours had much poorer prognosis for the first 3 years." (PMID 26703884, 2015). "YM155 significantly (P<0.05, n=7) prevented the tumorigenesis and reduced the tumor burden of Tgfbr1/Pten 2cKO mice compared with the vehicle-only group (n=6)." (PMID 26018732, 2015). "Of the 9 genes tested, 8 (THBS1, CYR61, CTGF, MXRA5, SPP1, LTBP2, TGFBR1 and COL11A1) were found by qRT-PCR to be significantly differentially expressed in tumor-associated fibroblasts, for a validation rate of 89%." (PMID 26575166, 2015). "In tumor bearing Tgfbr1/Pten 2cKO mice, PD-1 blockade increased MHC-II+, CD40+, CD86+ cells in spleen." (PMID 26573233, 2015). "Our previous work reported a spontaneous development of HNSCC in a mouse model by combined deletion of important tumor suppressors Pten and Tgfbr1." (PMID 26573233, 2015). "We looked at the tumor tissues from treated Tgfbr1/Pten 2cKO mice to see if the expression of IL-13Rα2 was decreased." (PMID 23421960, 2013). "We discovered that the tumors derived from these Tgfbr1/Pten double conditional knockout (2cKO) mice over-expressed IL-13Rα2, a high affinity receptor for IL-13 that can function as a tumor antigen." (PMID 23421960, 2013).
tumor (continued). "The Tgfbr1/Pten 2cKO mice were therefore tested with IL-13-PE (50 μg/kg b.i.d. on alternate days) for two weeks starting at an early point in tumor induction when carcinomas are first beginning to appear." (PMID 23421960, 2013). "With confirmation of the cytotoxic effects of IL-13-PE on cultured primary murine HNSCC tumor cells, we next decided to treat Tgfbr1/Pten 2cKO mice with i.p. injections of the recombinant immunotoxin." (PMID 23421960, 2013). "TGFBR1*6A (rs11466445) is a common polymorphic variant of the TGF-β receptor I gene and has been associated with tumour susceptibility." (PMID 19538729, 2009). "The aims of this study were to assess the association of TGFBR1*Int7G24A variant with CRC occurrence, patient age, gender, tumour location and stage." (PMID 19930569, 2009). "Conversely, downregulated genes included CD274 (PD-L1), TGFB1, and TGFBR1, which may reflect reduced transcriptional signatures of immune suppression within the tumor microenvironment." (PMID 41596590, 2026). "TGFBR1 inhibition with galunisertib or senolytic treatment reduces tumor progression driven by cisplatin-induced senescence, and concomitant use of TGFBR1 inhibitors with platinum-based chemotherapy reduces tumor burden and improves survival." (PMID 41634464, 2026). "High SHCBP1 expression is linked to greater infiltration of tumor-associated macrophage (TAM), CD4+ naïve T cells, CD8+ T cells, and neutrophils, as well as elevated levels of immune checkpoint proteins, including PD-L1 and TGFBR1 in multiple tumor types." (PMID 41009347, 2025). "In Tgfbr1/Pten 2cKO mice, thiram treatment also dramatically reduced tumor growth rate." (PMID 38730256, 2024). "In addition, B7-H4+ tumors in the isotype group have high expression of immunosuppressive genes including Tgfbr1 (TGFβ receptor), Cd33, and CD68 (tumor-associated macrophage markers)." (PMID 38687247, 2024). "Interestingly, in most tumor types, immunosuppression-related genes, especially TGFBR1 and PD-L1 (CD274), exhibited a specific correlation with the ORC6 expression." (PMID 36978046, 2023). "Further studies are warranted to compare optimal Tgfbr1 inhibition versus optimal Smad3 inhibition in the LLC tumor model, and whether a Tgfbr1 inhibitor provides any added benefit when given to Smad3-KO mice." (PMID 37002229, 2023). "Furthermore, in most tumor types, immunosuppression-related genes, especially TGFBR1 and PD-L1 (CD274), exhibited a specific correlation with the expression of ORC6." (PMID 36978046, 2023). "BMP8A and TGFBR1 were highly correlated with HER2 in the HER2 positive tumours." (PMID 37333824, 2023). "The ECM-related genes differentially expressed between TGFBR1-CA mice and controls may be further exploited to determine their potential value in tumor progression and diagnosis." (PMID 35565312, 2022). "To further understand how TGFβ signaling activation promotes ovarian GCT development, we performed transcriptomic analysis by RNA sequencing (RNA-seq) using ovaries from mice harboring constitutively active TGFBR1 and age-matched controls during early tumor development." (PMID 35565312, 2022). "Hypoxia-inducible lipid droplet-associated (HILPDA) was overexpressed in multiple tumor types, HILPDA was positively correlated with tumor-associated macrophages (TAM) infiltration, and immunosuppressive genes, such as PD-L1, PD-1, TGFB1, and TGFBR1." (PMID 36439512, 2022). "Together, these results indicate that TGFBR1 inhibition may be a novel therapeutic target for tumor treatment, consistent with previous results showing that downregulation of TGFBR1 suppresses cell proliferation, migration, and invasion in NSCLC." (PMID 33413277, 2021). "Furthermore, TGFBR1 affects tumor invasion and metastasis through the epithelial-mesenchymal pathway." (PMID 33413277, 2021).